RERE (arginine-glutamic acid dipeptide repeats)
Description:
Plays a role as a transcriptional repressor during development. May play a role in the control of cell survival. Overexpression of RERE recruits BAX to the nucleus particularly to POD and triggers caspase-3 activation, leading to cell death.
Synonyms: ARG; ARP; ATN1L; KIAA0458; DNB1; ATN2; NEDBEH
Tractability: PROTAC: UniProt records ubiquitination sites on it; ubiquitination databases record sites on it; its protein half-life has been measured.
Gene: Protein-coding gene on chromosome 1 (8,352,397 to 8,848,921, reverse strand). Ensembl gene ENSG00000142599.
Subcellular location: Nucleus
Subcellular location (Human Protein Atlas): Nuclear bodies; Nucleoplasm
Gene Ontology:
Molecular function: protein binding; transcription corepressor activity; chromatin binding; sequence-specific DNA binding; transcription coactivator activity
Biological process: negative regulation of DNA-templated transcription; positive regulation of DNA-templated transcription; regulation of DNA-templated transcription
Cellular component: nuclear body; nucleoplasm; nucleus; histone deacetylase complex
Genetic constraint (gnomAD): Loss-of-function variants: 33 observed, 96.03 expected, observed/expected ratio (o/e) 0.34, 90% interval 0.26 to 0.46. The synonymous counts are far from expectation, so gnomAD's model fits this gene poorly and the ratio says little. Missense variants: 1,699 observed, 1,719.8 expected, observed/expected ratio (o/e) 0.99, 90% interval 0.95 to 1.03. Synonymous variants: 875 observed, 705.28 expected, observed/expected ratio (o/e) 1.24, 90% interval 1.17 to 1.31.
Gene-disease validity (ClinGen):
ClinGen rates the evidence that RERE causes each of these diseases.
complex neurodevelopmental disorder with or without congenital anomalies (autosomal dominant): Definitive. A complex neurodevelopmental disorder that involves more than one phenotype associated with the central nervous system, including but not limited to intellectual disability, autism, and seizures (epilepsy), in addition to one or more structural or functional anomaly(ies) that develops prenatally.
Homologues: Orthologues: chimpanzee RERE (99% identical), macaque RERE (99% identical), dog RERE (95% identical), guinea pig RERE (94% identical), mouse Rere (94% identical), rat Rere (94% identical), tropical clawed frog rere (80% identical), zebrafish rerea (76% identical), rabbit RERE (70% identical), zebrafish rereb (48% identical), Drosophila melanogaster Gug (30% identical), Caenorhabditis elegans egl-27 (20% identical). Paralogues in human: ATN1 (33% identical).
Diseases named in the same sentence as RERE in open-access papers:
RERE is named in the same sentence as 51 diseases in open-access papers, as found by Europe PMC text mining. Sharing a sentence is not in itself a finding about the gene and the disease. The quoted sentences say what the papers report.
depression (4 papers, 2021 to 2023). "rs308107 has been associated with the intersection between major depression (MD) and intelligence, and expression of RERE in the brain." (PMID 37553252, 2023). "These included established loci in psychiatric genetics, such as NEGR1 with depression (P = 2.15 × 10−9) as well as RERE and FURIN with schizophrenia (P = 4.43 × 10−6 and P = 1.05 × 10−7, respectively)." (PMID 33481009, 2021). "Other genes that located outside of the MHC region, such as MAD1L1, RERE, SORCS3 and ANKK1, are associated with neuronal development and guidance of neuronal growth, transcriptional processes and other risk factors for depression, for example, obesity, smoking and abnormal physical development." (PMID 35354486, 2022).
schizophrenia (4 papers, 2018 to 2024). A major psychotic disorder characterized by abnormalities in the perception or expression of reality. "For instance, mutations in three genes our MR analyses linked to schizophrenia (RERE, KCNQ5) or anorexia (SUOX), respectively, are reported to cause monogenic diseases." (PMID 33417599, 2021). "Two separate cQTLs in MAD1L1 (PP(H4) > 0.98), one cQTL in AS3MT (PP(H4) = 0.98), one cQTL in TSNARE1 (PP(H4) = 0.94), and one cQTL in RERE (PP(H4) = 0.92) were found to colocalize with schizophrenia-associated variants." (PMID 30087329, 2018). "This suggests a mechanistic model in which the genetic regulation of RERE and its downstream effect on AUTS2 in astrocytes contribute to schizophrenia susceptibility." (PMID 39711543, 2024). "Our MR results suggest that inhibition of RERE and KCNQ5 could be used to treat schizophrenia and GPNMB to treat Parkinson’s disease whereas promotion of SUOX could be used to treat Anorexia and ACE to treat Alzheimer’s disease." (PMID 33417599, 2021).
breast carcinoma (3 papers, 2020 to 2022). "NMT1 and RERE were only highly expressed in PH026, and NMT1 was studied widely for breast cancer and showed suppression on initiation, proliferation and invasion of breast cancer cells." (PMID 35865544, 2022). "In primary breast cancers, circRNAs of CREBBP, CNOT2, and RERE and RNAi-mediated knockdown of circRNA circCNOT2 was shown to significantly reduce the viability of two breast cancer cell lines: MCF-7 and BT-474." (PMID 32467674, 2020).
asthma (2 papers, 2022 to 2024). "Specifically, three genes were associated with increased asthma risk in the lung and a decreased risk for asthma in the blood (i.e., RERE, UNC13D, and OIP5-AS1), and two genes (i.e., RP5-1115A15.1 and DEF6) had the opposite effect." (PMID 39628479, 2024). "We found PDCD11 was negatively associated with asthma-related TFs, including WT1, ZEB1, and RERE; ALDH18A1 was negatively associated with WT1 and RERE; SEC61A1 was negatively related with WT1 and ZEB1." (PMID 35169275, 2022). "Interestingly, asthma-related TFs, including WT1, ZEB1, and RERE, were negatively associated with most of hub genes." (PMID 35169275, 2022). "The network analysis revealed that transcription factor (TF) WT1, ZEB1, RERE, FOSL1, and miR-20a may be involved in the development of asthma." (PMID 35169275, 2022).
glaucoma (2 papers, 2016 to 2021). Increased pressure in the eyeball due to obstruction of the outflow of aqueous humor. "Four genes (CARD10, CWC27, RERE, and USP37) were nominally enriched (uncorrected P < 0.05) in the glaucoma cohort." (PMID 27896285, 2016).
Intellectual disability (2 papers, 2022 to 2024). "Mutations in the coactivator complex of the RAR/RXR gene, known as arginine–glutamic acid dipeptide repeats (RERE), have been identified in patients with syndromic intellectual disability and autistic features." (PMID 36143905, 2022).
microcephaly (2 papers, 2013 to 2023). A congenital or acquired developmental disorder in which the circumference of the head is smaller than normal for the person's age and sex. "This suggests that RERE deficiency may contribute to reduced brain size and the development of microcephaly in individuals with 1p36 deletions." (PMID 23451234, 2013). "It has been suggested that another gene: RERE (Arginine‐glutamic acid dipeptide repeats) may be responsible for microcephaly in 1p36DS." (PMID 36369750, 2023). "This suggests either a positional effect, indeed, deletions may be responsible for Topologically Associating Domains (TADs) disruption and chromatin disorganization leading to the deregulation of several genes or candidate genes for microcephaly as CDC42, SKI, or RERE." (PMID 36369750, 2023).
Obesity (2 papers, 2022 to 2024). Accumulation of substantial excess body fat. "Others among the top 10% high-scoring genes with an unknown role in the context of obesity include ERC2 (23.8), ZNF131 (23.8), NLGN1 (22.8), MLTT10 (22.8), RERE (22.8), and PDCH9 (22.8)." (PMID 38754426, 2024).
orofacial cleft (2 papers, 2023 to 2024). A disorder of facial skeleton that is characterized by cleft lip and/or cleft palate that result in feeding, speech and hearing problems caused by failures during development. "RERE heterozygous variants have been associated with neurodevelopmental disorder with or without anomalies of the brain, eye, or heart, with a loss of RERE function contributing to the development of orofacial clefts." (PMID 37845370, 2023). "A deficiency in RERE can lead to orofacial clefts, and in mice, the absence of RERE results in retinal degeneration and optic nerve atrophy." (PMID 39253079, 2024).
ventricular septal defect (2 papers, 2018 to 2023). The presence of a defect (opening) in the septum that separates the two ventricles of the heart. "It has been described that the haploinsufficiency of the RERE gene may be responsible for clinical signs recorded in 1p36 deletion, including heart defects notably ventricular septal defect." (PMID 36369750, 2023).
bipolar disorder (1 paper, 2017). A disorder of the brain that causes unusual shifts in mood, energy, activity levels and the ability to carry out day-to-day tasks. "This gene list includes new excellent candidates with putative links to bipolar disorder, including ADK, GTF2I, hnRNP-A1, HTRA2, PKD1 and RERE, which have been linked to various brain-related diseases." (PMID 28915787, 2017).
cardiac failure (1 paper, 2013). "Rereom/om mice die between E9.5 and E11.5 with unlooped hearts and signs of cardiac failure suggesting that RERE may play a role in early cardiovascular development." (PMID 23451234, 2013).
colon cancer (1 paper, 2021). "Lastly, upregulation of RERE mRNA as a consequence of miR‐22 inhibition resulted in increased migration and cell proliferation in colon cancer." (PMID 33797847, 2021).
epilepsy (1 paper, 2021). A brain disorder characterized by episodes of abnormally increased neuronal discharge resulting in transient episodes of sensory or motor neurological dysfunction, or psychic dysfunction. "RERE haploinsufficiency might also play a role in the epilepsy of some patients with the 1p36 deletion, but this gene is located proximally to CHD5 and deleted only in patients with very large deletions [8/50 in]." (PMID 33944996, 2021). "Thus, RERE haploinsufficiency would not explain the epilepsy of most patients with 1p36 deletion." (PMID 33944996, 2021).
Esophageal atresia (1 paper, 2018). A developmental defect resulting in complete obliteration of the lumen of the esophagus such that the esophagus ends in a blind pouch rather than connecting to the stomach. "We describe a neonate of an obese mother, diagnosed with type IV LTEC and type III esophageal atresia (EA), in which a 1p36 deletion including the RERE gene was detected." (PMID 30245899, 2018).
open-angle glaucoma (1 paper, 2022). Chronic outflow obstruction of the eye's drainage canals that can lead to increased internal eye pressure and optic nerve damage. "Moreover, most recently, 127 loci associated with open-angle glaucoma have been identified, with specific genes, such as RERE, VCAM1, ZNF638, SMAD6 potentially conferring open-angle glaucoma risk." (PMID 38983528, 2022).
opioid dependence (1 paper, 2022). "Further, two genes with differential mCpHs in OUD, RERE, and CFAP77, were previously identified in an epigenome-wide association study from our group evaluating differential 5mC associated with opioid dependence in whole blood samples from European–American women (n = 220)." (PMID 36745154, 2022).
psychosis (1 paper, 2019). "Bioinformatic analysis of WES and CGH-array data selected 15 common for psychosis phenotype damaging variants and 6 of them were rare mutations, including paternal 3p26.3-loss and 5 additional missense mutations located in ACSF2, MPRIP, PHC1, PER3, and RERE genes." (PMID 30710087, 2019).
renal agenesis (1 paper, 2013). Renal agenesis (RA) is a form of renal tract malformation characterized by the complete absence of development of one or both kidneys (unilateral RA or bilateral RA respectively), accompanied by absent ureter(s). "This suggests that RERE deficiency may cause renal agenesis in mice through disruption of retinoic acid signaling." (PMID 23451234, 2013).
urothelial carcinoma (1 paper, 2022). A malignant neoplasm derived from the transitional epithelium of the urinary tract (urinary bladder, ureter, urethra, or renal pelvis). "In line with the sensitivity of basal urothelial carcinoma to HDAC inhibitors, we identified the arginine–glutamic acid dipeptide repeats gene (RERE) as a leading regulon active in basal BLCA cell lines (p < 0.001)." (PMID 36142576, 2022).
vitiligo (1 paper, 2022). Generalized well circumscribed patches of leukoderma that are generally distributed over symmetric body locations and is due to autoimmune destruction of melanocytes. "Based on our prioritization pathway, we found that genetic variants of FGFR10P, SUOX, CDK5RAP1 and RERE have the potential to directly or indirectly contribute to the disease pathogenesis, suggesting that hitherto unexplored biological pathways may be involved in imparting vitiligo risk." (PMID 36008553, 2022). "Our analysis revealed genes like FGFR10P, SUOX, CDK5RAP1 and RERE that have never been implicated in vitiligo previously to have strong potentials to contribute to the disease pathogenesis." (PMID 36008553, 2022). "On the contrary, CDK5RAP1 and RERE have neither been previously implicated in vitiligo and/or pigmentation or were found to interact with known vitiligo related genes or any of the other prioritized genes." (PMID 36008553, 2022).
neurodevelopmental disorder (7 papers, 2018 to 2025). A behavioral and cognitive disorder with onset during the developmental period that involves impaired or aberrant development of intellectual, motor, or social functions. "Mutations within the RERE gene itself are associated with neurodevelopmental disorders." (PMID 40155636, 2025). "Loss-of RERE function results in an early-onset neurodevelopmental disorder with anomalies in the brain, eye and heart (OMIM 605226), and haploinsufficiency for RERE variants with assumed milder impact are believed to contribute to neurological abnormalities in adults." (PMID 33417599, 2021). "Autosomal dominant variants with a parent affected with significant neurodevelopmental disorder were identified in two families (TCF20, paternally inherited, and RERE, maternally inherited)." (PMID 38256266, 2024). "Recently, mutations affecting RERE have been shown to cause a new genetic syndrome, neurodevelopmental disorder with or without anomalies of the brain, eye or heart (NEDBEH)." (PMID 30061196, 2018).
tumor (4 papers, 2011 to 2023).
cancer (3 papers, 2013 to 2022). A tumor composed of atypical neoplastic, often pleomorphic cells that invade other tissues. "Six additional non-synonymous SNVs were discovered and confirmed, including variants in AKAP1, PCNT and RERE, all of which have been implicated in cancer." (PMID 23803469, 2013). "We selected those genes with functions known to be associated with cancer of which there were 12—SNVs: NOTCH2, PIK3CG, IL2RB, BAI3, FREM2 and RERE; indels: UTRN, CDHR3, NCOA5, CABYR, HOTAIR and FOLH1." (PMID 26017033, 2015). "It is known that to counteract pro-apoptotic stimuli, cancer cells might activate pro-survival mechanisms, an event that could explain the decreased expression levels of EI24 and RERE proteins in response to CK2 inhibition with CIGB-300." (PMID 35359604, 2022).
cardiovascular diseases (1 paper, 2024). "However, the roles of UNC119B, RERE, and FNDC3B in cardiovascular diseases are not known." (PMID 38303056, 2024).
RERE also shares sentences with these, for which no sentence is quoted: Anorexia (2 papers); autism (2); Alzheimer disease (1); Anxiety (1); cardiomyopathy (1); CHARGE syndrome (1); choanal atresia (1); Chromosome Disorder (1); developmental delay (1); fibrosis (1); growth deficiency (1); hearing loss (1); hematological malignancies (1); iris coloboma (1); language delay (1); left ventricular noncompaction (1); mental disorder (1); microphthalmia (1); Motor delay (1); neurological disorders (1); osteoporosis (1); Parkinson disease (1); progressive sensorineural hearing loss (1); psychiatric disorder (1); retinal degeneration (1); Seizure (1).